GHRH (growth hormone releasing hormone)
Diseases named in the same sentence as GHRH in open-access papers (continued):
Sharing a sentence is not in itself a finding about the gene and the disease.
Obesity (24 papers, 2006 to 2025). Accumulation of substantial excess body fat. "Hormonal GHRH, somatostatin, or ghrelin dysregulation have been suggested as the neuroendocrine changes that underlie decreased plasma GH levels in obesity." (PMID 39981480, 2025). "An acquired functional decrease in GH production and GH response to stimuli (such as insulin-induced hypoglycemia, arginine, arginine-GHRH, sleep, or exercise) is linked to obesity; this decrease is reversible following substantial weight loss." (PMID 39981480, 2025). "GNAS mutations can variably impact height as impaired MC4R signalling can lead to obesity with tall stature, whereas impaired GHRH signalling results in GH deficiency and short stature." (PMID 39104441, 2024). "For example, growth hormone releasing hormone analogs—such as tesamorelin—have previously been shown to lead to a selective reduction of VAT in patients with obesity or HIV-associated lipodystrophy." (PMID 35773277, 2022). "In accordance with these data, the use of GHRH analog to increase endogenous GH in adults with obesity and GH deficiency has been proposed, and it has shown a positive effect in reducing visceral fat, body fat mass and systemic inflammation." (PMID 36557260, 2022). "After 8 weeks, ACP cystic fluid caused growth retardation, increased the obesity index, and decreased plasma GH and GHRH levels." (PMID 35525962, 2022). "GH peak response to GHRH-arginine and cardiovascular risk factors, including obesity, insulin resistance, low levels of high density lipoprotein (HDL) cholesterol, elevated triglycerides, and hypertension." (PMID 16886956, 2006). "Obesity is associated with an acquired functional reduction in GH secretion and in GH response to stimulus (e.g., insulin-induced hypoglycemia, arginine, arginine-GHRH, sleep, or exercise), which is reversible after significant weight loss." (PMID 31608009, 2019). "GHRH is intricately involved in metabolic processes, and its dysregulation can lead to or exacerbate various metabolic disorders, including obesity, type 2 diabetes, cardiovascular diseases, metabolic syndrome, and growth hormone deficiency (GHD)." (PMID 39560873, 2024). "For instance, changes in corticotrophin-releasing factor (CRF), luteinizing hormone-releasing hormone (LHRH or GnRH), and growth hormone-releasing hormone (GHRH) secretion are apparently linked to neuroinflammation, obesity, and hyperinsulinemia." (PMID 39684795, 2024). "After 8 weeks, the mice in cystic fluid group showed growth retardation and obesity tendency, and the decrease in serum GH and GHRH and the short-term increase in food intake were corresponded to the appropriate phenotype." (PMID 35525962, 2022). "Among the underlying neuroendocrine alterations of low plasma GH levels in obesity, hormonal GHRH, somatostatin, or ghrelin dysregulation have been proposed." (PMID 31608009, 2019). "For example in Zucker rats, a genetic model of obesity, both GHRH and SRIF gene expression are suppressed in obese relative to lean rats, indicating hypothalamic involvement in the hyposomatotropism." (PMID 25789758, 2015). "As for other animals and humans, there was evidence of central hyposomatotropism in response to obesity, as GHRH gene expression was suppressed by the HFD." (PMID 25789758, 2015). "This enhances GH response to GHRH both in normal subjects, and in many instances of impaired GH secretion, including obesity." (PMID 24723909, 2014). "The use of somatostatin vaccines for treatment of obesity is based upon previous studies using GH therapy and the accepted endocrine model of somatostatin to down-regulate growth hormone releasing hormone (GHRH), GH and IGF-1." (PMID 22958753, 2012). "The pathogenesis of reduced GH secretion in obesity is unknown, but suggested mechanisms include increased hypothalamic somatostatinergic tone or GHRH hypoactivity, hyperinsulinaemia, or elevated circulating free fatty acids." (PMID 22899919, 2012).
Obesity (continued). "We aimed to investigate the relationships between GH secretory capacity, evaluated with GHRH + arginine stimulation test, and bone parameters, assessed with a dual-energy X-ray absorptiometer, in a population of adult female patients affected by overweight and obesity." (PMID 39274277, 2024). "Therefore, the present study was carried out with the aim of determining the proportion of individuals with low serum IGF-1 levels and/or failing to respond to the combined GH-releasing hormone (GHRH) plus arginine test in a cohort of FM subjects with severe obesity." (PMID 28744309, 2017). "In conclusion, the present study shows that a not negligible subpopulation (25%) of patients with both FM and severe obesity has low IGF-1 SDS values, 12.5% failing also to normally respond to the GHRH plus arginine test." (PMID 28744309, 2017). "Patients with T2DM and obesity show a significantly lower GH response to GHRH in comparison to patients with T2DM without obesity." (PMID 33586392, 2021). "This study aims to evaluate the relationships between GH secretory capacity, tested with the GHRH plus arginine test, and bone quantitative and qualitative parameters and body composition, assessed by DXA, in a population of women affected by overweight or obesity." (PMID 39274277, 2024).
neuroendocrine tumors (23 papers, 2013 to 2026). "Vast majority of GHRH-producing tumors are neuroendocrine tumors, quite often associated with MEN-1 syndrome." (PMID 35757397, 2022). "The condition can also arise from ectopic growth hormone-releasing hormone (GHRH) secretion by neuroendocrine tumors located in the pancreas and thymus or bronchial carcinoids." (PMID 40791994, 2025). "The sources of ectopic growth hormone-releasing hormone (GHRH) include neuroendocrine tumors (NETs) arising from the pancreas, lung, thymus and appendix, pheochromocytomas, paragangliomas, and hypothalamic choristomas and gangliocytomas." (PMID 39449742, 2024). "This leads to a search for a source of ectopic growth hormone-releasing hormone (GHRH), confirmed by a grossly elevated circulating GHRH blood level and the presence of a pancreatic mass indicative of a neuroendocrine tumor secreting GHRH ectopically." (PMID 37166678, 2023). "Ectopic GHRH derives most commonly from functional neuroendocrine tumors (NETs) originating in the lung or the pancreas and results in pituitary hyperplasia and excess GH secretion." (PMID 35757397, 2022). "In rare cases (less than 1%), neuroendocrine tumours producing growth hormone releasing hormone (GHRH) or ectopic GH-secreting tumours have been described." (PMID 33805450, 2021). "The overall prognosis of these patients with GHRH-secreting tumors is excellent, with 85% survival at five years, as these tend to be well-differentiated neuroendocrine tumors." (PMID 31766255, 2019). "GHRH analogues have been shown to augment VEGF-A secretion in the contexts of neuroendocrine tumor cells and myocardial infarction." (PMID 27774107, 2016). "GHRH has been shown to stimulate angiogenesis in human neuroendocrine tumors by promoting VEGF secretion." (PMID 27774107, 2016). "The term “ectopic acromegaly” includes neuroendocrine tumors secreting GH releasing hormone (GHRH), usually located in the lungs, thymus and endocrine pancreas." (PMID 24119925, 2013). "Similarly, in another retrospective study comprising 30 cases of GHRH-secreting neuroendocrine tumors, radiological hyperplasia of the pituitary was reported in 80% (24/30) of cases." (PMID 39449742, 2024). "Very rarely, cross-sectional imaging and measurement of GH releasing hormone (GHRH) may be needed to identify an ectopic GHRH-secreting neuroendocrine tumor (DR)." (PMID 37923946, 2024). "In addition, childhood-onset somatotropinomas are extremely rare in the setting of MEN1 syndrome, in which pediatric GH excess is more likely to arise from GHRH-secreting neuroendocrine tumors." (PMID 31125088, 2019). "Both central hypothalamic tumours (usually gangliocytomas) and peripheral neuroendocrine tumours could secrete growth hormone–releasing hormone (GHRH), inducing somatotroph proliferation (and very rarely, the formation of an adenoma), with resultant elevations in levels of growth hormone and IGF-I." (PMID 26023776, 2015). "Histopathology was suggestive of a neuroendocrine tumor, with immunohistochemistry positive for GHRH and negative for prolactin." (PMID 39449742, 2024). "It is mainly caused by pituitary adenoma, which causes excessive and uncontrolled secretion of growth hormone (GH); however, the presence of neuroendocrine neoplasm (NEN) in any location, which secretes GH or growth hormone-releasing hormone (GHRH) is also possible." (PMID 37373574, 2023).
pituitary adenoma (23 papers, 2010 to 2026). "Approximately 98% are caused by pituitary adenomas that secrete growth hormone (GH), and 2% are caused by pituitary hyperplasia, ectopic growth hormone or ectopic growth hormone releasing hormone (GHRH) secretion." (PMID 33869029, 2021). "This case suggests that GHRH secretion can be associated with pituitary hyperplasia, which may be followed by pituitary adenoma formation." (PMID 34591404, 2021). "X-LAG, which may occur isolated or associated with FIPA, is characterized by pituitary adenomas or pituitary hyperplasia producing most frequently increased levels of GH, GH releasing hormone (GHRH), and prolactin." (PMID 31365626, 2019). "The remote possibility of the presence of an extrapituitary GHRH-producing tumor must be considered because these lesions, in addition to increasing GH levels, can cause a somatotropic hyperplasia and suggest the presence of a pituitary adenoma on imaging studies." (PMID 23209463, 2012). "Pituitary hyperplasia due to ectopic GHRH-secreting tumors can radiologically mimic pituitary adenoma, and apoplexy is extremely unusual but can lead to rapid shrinkage of the tumor, unlike eutopic somatotropinomas." (PMID 39449742, 2024). "Furthermore, GHRH antagonists have been shown to enhance chemotherapy efficacy in various cancers, including lung cancer, pleural mesothelioma, and pituitary adenomas." (PMID 40244089, 2025). "Another possibility is that the undifferentiated ganglion cells discarded by the neurohypophysis transformed into tumor cells due to GHRH, which was excessively produced by the hypothalamus, while the pituitary cells formed the pituitary adenoma by GHRH stimulation." (PMID 25013498, 2014). "In our patient, the absence of both pituitary adenoma and hyperplasia, combined with normal GHRH levels, supported the diagnosis of GH-secreting ectopic acromegaly." (PMID 41573472, 2025). "Many studies have demonstrated that the antagonists of growth hormone-releasing hormone (GHRH) exert inhibitory activities in a variety of experimental cancers; however, their potential antitumor role in pituitary adenomas (PAs) remains largely unknown." (PMID 34439107, 2021). "Additionally, if the GH excess was the result of GHRH, it would have resulted in pituitary GH-secreting cell hyperplasia, rather than a distinct pituitary adenoma, which is the case in our patient." (PMID 20864785, 2010). "Among the three remaining patients, one had a GHRH secreting pulmonary NET and two had an empty sella and it was not possible to identify a pituitary adenoma." (PMID 33164134, 2021).
diabetes (19 papers, 2012 to 2026). "Gastritis caused by H. pylori may affect the secretion of gastric-related hormones, such as leptin and growth hormone-releasing hormone, as well as gastrin and somatostatin, which may affect the susceptibility to diabetes." (PMID 31583248, 2019). "Another potential target for GHRH antagonists could be diabetic retinopathy, which is the main cause of blindness in patients with diabetes and diabetic nephropathy (glomerulosclerosis)." (PMID 27777568, 2016). "For example, GHRH antagonism may improve some of the lipid, renal, and vascular complications of low insulin-associated diabetes." (PMID 27777568, 2016). "Thus, GHRH agonists might represent a new pharmacological strategy for treatment of diabetes-associated cardiovascular complications." (PMID 39560873, 2024). "Preclinical studies demonstrate that synthetic GHRH analogues like MR-409 mitigate vascular calcification in diabetes, enhance cardiac repair post-myocardial infarction, and restore diastolic function in heart failure through calcium-handling modulation." (PMID 42292828, 2026). "MR409, a synthetic growth hormone-releasing hormone (GHRH) analogue, has demonstrated therapeutic potential in enhancing islet cell transplantation efficacy in diabetes mice and exerts beneficial effects on cardiovascular diseases." (PMID 40926987, 2025). "Prof. Andrew Schally and his team of chemists have indeed developed both agonistic and antagonistic molecules of GHRH, which showed promise in regenerative medicine, aiding tissue repair, cardiac function, islet cell survival in diabetes and neuroprotection." (PMID 40095316, 2025). "GHRH agonists have been shown to promote β-cell proliferation and survival in both in vitro studies and animal models of diabetes and transplantation, indicating their potential as an alternative approach." (PMID 39560873, 2024). "GHRH agonists have shown promise in promoting tissue regeneration, improving cardiac function, and enhancing islet survival in diabetes." (PMID 39592529, 2024). "In conclusion, Hex is capable of recovering impaired pulsatile GH secretion through increasing hypothalamic GHRH activity in STZ-induced diabetes, suggesting a possible mechanism in improving metabolic balance in diabetes." (PMID 30297647, 2018). "This review considers the role of GHRHR in the beta-cell and addresses the unique engineered GHRH agonists and antagonists for treatment of type 2 diabetes mellitus." (PMID 27777568, 2016). "Among the peripheral activities, recent studies demonstrate a novel ability of GHRH analogs to increase and preserve insulin secretion by beta-cells in isolated pancreatic islets, which makes them potentially useful for diabetes treatment." (PMID 27777568, 2016). "Therefore, GHRH and its agonistic analogs, including tesamorelin, MR-409 and JI-38 have been developed as potential therapeutic agents to treat diabetes, cancers, cardiovascular and other diseases." (PMID 39934495, 2025). "Their extensive work led to the development of GHRH agonists and antagonists, which have shown therapeutic potential in a wide range of fields, including cardiovascular diseases, diabetes and metabolic disorders, oncology, neurodegenerative diseases, and regenerative medicine." (PMID 40095316, 2025). "Accordingly, GHRH agonists offer a new therapeutic approach to treating diabetes." (PMID 39934495, 2025). "In this review, I analyse the FDA approval of natural peptides, as well as engineered peptides for diabetes treatment, growth-hormone-releasing hormone (GHRH), cholecystokinin (CCK), adrenocorticotropic hormone (ACTH), and α-melanocyte stimulating hormone (α-MSH) peptide analogues." (PMID 38540684, 2024). "GHRH is involved in the regulation of insulin secretion from the pancreas and abnormal GHRH signaling can impair insulin secretion, leading to hyperglycemia and contributing to the development or worsening of diabetes." (PMID 39560873, 2024).
diabetes (continued). "The potential therapeutic applications of GHRH agonists extended to diabetes as well." (PMID 39592529, 2024). "We conclude that interventions targeting mitochondrial fission in GHRH neurons may offer a new pathway to prevent HAAF in patients with diabetes." (PMID 33148883, 2020). "The objective of this study was to determine whether tesamorelin, a stabilized growth hormone-releasing hormone analogue, would alter insulin sensitivity or control of diabetes." (PMID 28617838, 2017). "Remarkable results from the study of new GHRH agonists in wound healing and cardiovascular performance could also provide novel treatments in patients with diabetes." (PMID 27777568, 2016). "Remarkable results from the study of new GHRH agonists in wound healing and cardiovascular performance could also suggest novel treatments in patients with diabetes or perhaps help understand the pathways involved." (PMID 27777568, 2016). "Finally, we observed an unexpected trend, in which genes increased and decreased in GHRH-KO mice were similarly altered in mice with streptozocin-induced diabetes (BALB/c background)." (PMID 24175087, 2013). "Because tesamorelin, a stabilized GHRH analogue, has been previously shown to stimulate GH secretion in a physiological manner, this study was conducted in patients with type 2 diabetes to assess its potential effects on insulin sensitivity and diabetes control." (PMID 28617838, 2017). "As the present study also used a single dose of STZ to induce diabetes, it was believed that depressed secretion of pulsatile GH in the STZ-treated group was a result of decreased hypothalamic GHRH activity with increased somatostatin tone." (PMID 30297647, 2018). "However, administration of the GHRH analog tesamorelin to type 2 diabetes patients showed no changes in insulin response or diabetes control, despite decreasing cholesterol levels, suggesting that the effect is independent of the GHRH/GH/IGF-1 axis." (PMID 39560873, 2024).